PTHLH (parathyroid hormone like hormone)
Description:
Neuroendocrine peptide which is a critical regulator of cellular and organ growth, development, migration, differentiation and survival and of epithelial calcium ion transport. Acts by binding to its receptor, PTH1R, activating G protein-coupled receptor signaling. Regulates endochondral bone development and epithelial-mesenchymal interactions during the formation of the mammary glands and teeth (By similarity). Required for skeletal homeostasis. Promotes mammary mesenchyme differentiation and bud outgrowth by modulating mesenchymal cell responsiveness to BMPs. Up-regulates BMPR1A expression in the mammary mesenchyme and this increases the sensitivity of these cells to BMPs and allows them to respond to BMP4 in a paracrine and/or autocrine fashion (By similarity). BMP4 signaling in the mesenchyme, in turn, triggers epithelial outgrowth and augments MSX2 expression, which causes the mammary mesenchyme to inhibit hair follicle formation within the nipple sheath (By similarity). Promotes colon cancer cell migration and invasion in an integrin alpha-6/beta-1-dependent manner through activation of Rac1. [Osteostatin]: Potent inhibitor of osteoclastic bone resorption.
Synonyms: PTHrP; PLP; HHM; PTHR; BDE2
Tractability: Small molecule: a structure with a bound ligand is known. Antibody: a drug acting on it is in phase 2 or 3 trials; UniProt places it where antibodies can reach, with high confidence; its Gene Ontology location is reachable by antibodies, with high confidence; UniProt predicts a signal peptide or a membrane-spanning region.
Target class: Secreted protein
Gene: Protein-coding gene on chromosome 12 (27,958,084 to 27,972,755, reverse strand). Ensembl gene ENSG00000087494.
Subcellular location: Secreted; Cytoplasm; Nucleus
Subcellular location (Human Protein Atlas): Cytosol; Nucleoplasm; Golgi apparatus; Predicted to be secreted
Pathways (Reactome):
Signal Transduction: Class B/2 (Secretin family receptors); G alpha (s) signalling events
Gene Ontology:
Molecular function: hormone activity; peptide hormone receptor binding; protein binding
Biological process: adenylate cyclase-activating G protein-coupled receptor signaling pathway; G protein-coupled receptor signaling pathway; negative regulation of chondrocyte development; negative regulation of chondrocyte differentiation; regulation of gene expression; skeletal system development; cAMP metabolic process; cell-cell signaling; epidermis development; female pregnancy; negative regulation of cell population proliferation; osteoblast development; positive regulation of cell population proliferation; regulation of chondrocyte differentiation; bone mineralization
Cellular component: cytoplasm; cytosol; extracellular region; nucleoplasm; nucleus
Genetic constraint (gnomAD): Loss-of-function variants: 4 observed, 16.39 expected, observed/expected ratio (o/e) 0.24, 90% interval 0.12 to 0.56. The upper end of that interval is the gene's LOEUF score, 0.56, which puts it in group 2 of 6, group 1 being the genes least tolerant of losing a copy. Missense variants: 204 observed, 217.04 expected, observed/expected ratio (o/e) 0.94, 90% interval 0.84 to 1.06. Synonymous variants: 89 observed, 91.22 expected, observed/expected ratio (o/e) 0.98, 90% interval 0.82 to 1.16.
Homologues: Orthologues: chimpanzee PTHLH (99% identical), macaque PTHLH (99% identical), dog PTHLH (91% identical), pig PTHLH (90% identical), rabbit PTHLH (86% identical), rat Pthlh (86% identical), mouse Pthlh (85% identical), guinea pig PTHLH (82% identical), tropical clawed frog pthlh (45% identical), zebrafish pthlha (42% identical), zebrafish pthlhb (27% identical).
Diseases named in the same sentence as PTHLH in open-access papers:
PTHLH is named in the same sentence as 284 diseases in open-access papers, as found by Europe PMC text mining. Sharing a sentence is not in itself a finding about the gene and the disease. The quoted sentences say what the papers report.
Hypercalcemia (264 papers, 1991 to 2026). An abnormally increased calcium concentration in the blood. "We provide further evidence that the PTHLH gene product, PTHrP, causes the hypercalcemia that frequently complicates ccRCC 42,44-46." (PMID 40964365, 2025). "In cancer patient, aberrant PTHLH expression is the predominant cause of hypercalcemia as well as cancer cachexia." (PMID 28120940, 2017). "It has been well characterized that the main cause of hypercalcemia in RCC is the aberrant secretion of PTHLH from tumor cells 4–6." (PMID 24861371, 2014). "Cancer-associated hypercalcemia correlates with increased parathyroid hormone-like peptide (PTHLH) levels and PTHLH levels are elevated during PCa progression." (PMID 24586868, 2014). "PTHLH is associated with malignancy-related hypercalcemia, lactation, the expression of PHLDA2 is upregulated in osteosarcoma progression." (PMID 24068962, 2013). "Tumor-associated secretion of PTHLH is causally implicated in malignancy-associated hypercalcemia, as well as in the initiation, progression and metastasis of breast cancer." (PMID 24324612, 2013). "The minor incidences of hypercalcemia observed in this study appear to be vitamin D-independent and may be linked to increases in PTHLH levels during PCa progression in TRAMP mice." (PMID 24586868, 2014). "Further, we show that the increased PTHLH expression is both necessary and sufficient for the induction of hypercalcemia and cachexia in preclinical orthotopic cell line tumor models." (PMID 40964365, 2025). "While FGF23 represses CYP27B1 and activates catabolism of active hormone, increased PTHLH secretion can lead to hypercalcemia via inactivation of VDR." (PMID 37242266, 2023). "Over 80 percent of the cancer patients with hypercalcemia have an increased serum PTHLH concentration." (PMID 28120940, 2017). "Despite the robust evidence of a triangular relationship among high PTHLH secretion, hypercalcemia, and patient poor prognosis, the relevance of PTHLH expression to the survival of patients with RCC was not clear in the previous analyses." (PMID 24861371, 2014). "Previous studies have demonstrated that hypercalcemia in RCC is mainly induced by the aberrant secretion of parathyroid hormone-like hormone (PTHLH) from cancer cells." (PMID 24861371, 2014). "Moreover, PTHLH may promote cancer hypercalcemia and cachexia in HNSCC patients." (PMID 28120940, 2017). "Mice with DOXi PTHLH tumors, but not DOXi EV tumors, rapidly developed cachexia and hypercalcemia, requiring euthanasia within several weeks, if fed the DOX-containing chow." (PMID 41315757, 2026). "In this study, we demonstrated that high serum Ca and high PTHLH expression in tumors, the major etiology of hypercalcemia in malignancy, were observed in clear cell RCCs but not in other non clear cell tumors when using the 2004 WHO renal tumor classification." (PMID 24861371, 2014). "As was true for OSRC-2 cells, RXF393 cells induced cachexia and hypercalcemia in subcutaneous xenograft assays and these two phenotypes were reversed by PT2399 and prevented by CRISPR KO of PTHLH without commensurate changes in tumor growth." (PMID 40964365, 2025).
breast carcinoma (215 papers, 1995 to 2026). "This is important since the gene coding for PTHrP (PTHLH) has been consistently identified as a breast cancer susceptibility locus." (PMID 41700599, 2026). "Two genome-wide association studies have also found the PTHrP gene, PTHLH, in a susceptibility locus for both ER+ and ER- breast cancer." (PMID 37046642, 2023). "Breast cancer fine-mapping analysis has identified DA lead SNP rs7297051 as one of the four independent association signals of breast cancer at chromosome 12p11, which is approximately 50 kb upstream of the PTHLH gene." (PMID 35414113, 2022). "Administering FAKi and genetically rendering FAK deficient in breast cancer cells abrogated the interaction between TGFβRI and TGFβRII and thereby blocked phosphorylation of Smad2 and expression of its downstream effector PTHLH." (PMID 35538070, 2022). "Given that PTHLH has been defined as a breast cancer susceptibility gene in GWAS studies, it is important to clarify the molecular mechanisms by which PTHrP affects breast cancer cell behavior." (PMID 35440032, 2022). "The index SNP lies in an approximately 300-kb linkage disequilibrium (LD) block, containing one known breast cancer associated gene that encodes parathyroid hormone-like hormone (PTHLH)." (PMID 27459855, 2016). "PTHLH encodes a 36-amino-acid mature peptide strongly implicated in multiple aspects of breast cancer progression." (PMID 25633981, 2015). "For example, PTHLH was found to be up-regulated in breast cancers by genome-wide association studies (GWAS)." (PMID 25539663, 2014). "Cancer-specific differential expression PTHLH transcript isoforms has been reported in prostate and in other cancers, and the ratio of PTHLH isoforms has been associated with breast cancer outcome." (PMID 24324612, 2013). "We have shown that two SNPs (rs12173570 near ESR1 and rs12371778 near PTHLH) are associated with breast size; these two SNPs have previously been associated with breast cancer risk." (PMID 22747683, 2012). "Only SNP rs10771399 near PTHLH was associated with breast cancer risk for BRCA1 mutation carriers (per-allele hazard ratio (HR) = 0.87, 95% CI: 0.81 to 0.94, P-trend = 3 × 10-4)." (PMID 22348646, 2012). "The associations with breast cancer risk remained essentially unchanged in the competing risk analysis, with only the PTHLH SNP rs10771399 being significantly associated with breast cancer risk." (PMID 22348646, 2012). "In a large analysis including two genome-wide association studies from 41 case–control studies through the Breast Cancer Association Consortium (BCAC) and nine breast cancer genome-wide association studies, PTHLH was identified as a susceptibility locus in both ER+ and ER− breast cancer." (PMID 33828987, 2021). "Additionally, activation of Gli2 and Gli2 is dependent on SMAD3 in several cell lines including keratinocytes and breast carcinomas, and activation of the Gli2 target gene PTHLH (encoding parathyroid hormone-related protein) occurs independently of canonical Hh signaling." (PMID 37954979, 2023). "In addition, genome-wide association (GWAS) studies have implicated the PTHLH (PTHrP) gene as a breast cancer susceptibility locus, suggesting that it may contribute to early steps in transformation and/or cancer progression." (PMID 35440032, 2022). "The upregulated expression of oncogenic PTHLH is associated with poor prognosis owing to its role in promoting tumour initiation, growth, angiogenesis, metastasis, and chemoresistance in pancreatic, colorectal, intrahepatic cholangiocarcinoma, head and neck, osteosarcoma, and breast cancers." (PMID 35406121, 2022). "Integrated molecular analysis of these tumours revealed important genes – including those that encode matrix metalloproteinase-3 (MMP-3) and parathyroid hormone-like hormone (Pthlh) – whose dysregulation might be causally involved in metastatic dissemination of breast cancer." (PMID 25633981, 2015).
breast carcinoma (continued). "In BRCA2 mutation carriers, evidence for a breast cancer association with genetic variants in PTHLH has been restricted previously to ER-negative tumors; however, the novel susceptibility variant we reported here was associated with risk of ER+ and ER- breast cancer." (PMID 23544012, 2013). "We also examined the correlation between the expression of EZH2 and the downstream effector PTHLH in bone metastasis tissues obtained from breast cancer patients in the GSE14020 dataset." (PMID 35538070, 2022). "DLC1 was found to repress PTHLH transcription and secretion and eventually lead to decrease breast cancer bone metastasis." (PMID 36185184, 2022). "Genome-wide association studies have implicated both the parathyroid hormone-like hormone (PTHLH) and the PTHR1 loci as breast cancer susceptibility genes." (PMID 35846378, 2022). "Sorting out the details of when and how PTHrP affects different breast cancers in different fashions will be critical to understanding the reported association between the PTHLH gene and breast cancer in GWAS studies." (PMID 35440032, 2022). "To further explore how EZH2 facilitates PTHLH and TGFβ signaling in breast cancer cells, we detected pS465/467-Smad2 and pT180/Y182-p38 MAPK levels in MDA-MB-231 sublines." (PMID 35538070, 2022). "A recent study reported that the TGFβ1 signalling pathway upregulates the expression of PTHLH in lung and breast cancers." (PMID 35406121, 2022). "Smad3, a transcription factor, upregulates the transcription of PTHLH by binding to the proximal PTHLH promoter region in response to TGFβ1 signalling in breast cancer cells and consequently promotes bone metastasis." (PMID 35406121, 2022). "Activated Smad3 promotes the transcription of PTHLH in response to TGFβ1, which is also known as a cachexia-inducing factor, in breast cancer." (PMID 35406121, 2022). "A germline polymorphism near PTHLH was associated with increased risk for the development of both sporadic and BRCA1-mutation-associated breast cancer, and tumour expression of PTHLH promotes the formation of osteolytic lesions in bone." (PMID 25633981, 2015). "For the 12p11 (PTHLH), 5q11 (MAP3K1), and 9p21 (CDKN2A/B), we found uncorrelated SNPs that had stronger associations than the originally identified SNP in the breast cancer susceptibility region that should be replicated in the general population." (PMID 23544012, 2013). "We replicated previously reported breast cancer susceptibility alleles in these BRCA2 mutation carriers and for several regions (including FGFR2, MAP3K1, CDKN2A/B, and PTHLH) identified SNPs that have stronger evidence of association than those previously published." (PMID 23544012, 2013). "Besides PTHLH, IL-8 is a cytokine that also regulates osteolysis in breast cancer bone metastasis." (PMID 35538070, 2022). "Recent genome-wide association studies of breast cancer have identified eight additional breast cancer susceptibility loci: rs1011970 (9p21, CDKN2A/B), rs10995190 (ZNF365), rs704010 (ZMIZ1), rs2380205 (10p15), rs614367 (11q13), rs1292011 (12q24), rs10771399 (12p11 near PTHLH) and rs865686 (9q31.2)." (PMID 22348646, 2012). "Parathyroid hormone-like hormone (PTHLH, also named PTHRP) is an essential mediator of breast cancer bone metastasis, and metastatic cancer cells secrete PTHLH into the bone microenvironment to activate osteolysis." (PMID 35538070, 2022). "DLC1 was reported to suppress parathyroid hormone-like hormone (PTHLH) transcription and secretion through Rho-TGF-β crosstalk, leading to attenuate osteoclast maturation and reduce breast cancer bone metastasis." (PMID 36185184, 2022). "Comprehensive RNA sequencing data collected as a part of the MET500 cohort was analyzed for gene expression of Gli2, PTHLH, ITGB1, and ITGA2 in metastatic breast cancer samples." (PMID 34199096, 2021). "Our findings also suggest a possible interrelation between PTHLH and CCDC91 in the etiology of breast cancer." (PMID 27459855, 2016).
breast carcinoma (continued). "Interestingly, ANGPTL4, PTHLH and SERPINE1 have all been shown to be involved in breast cancer progression and metastasis." (PMID 24330518, 2013). "Spearman correlation analysis of gene signatures in metastatic biopsies of breast cancer reveal a significant (p < 0.001) negative correlation between PTHLH and ITGA2 (p < 0.001), PTHLH and ITGB1 (p < 0.01), Gli2 and ITGA2 (p < 0.001), and Gli2 and ITGB1 (p < 0.0001)." (PMID 34199096, 2021).
prostate carcinoma (71 papers, 2001 to 2025). A carcinoma that arises from epithelial cells of the prostate gland. "Through scratch assays, we observed that overexpression of PTHLH increased the migratory ability of prostate cancer cells, whereas PTHLH-knockdown resulted in reduced cell migration." (PMID 37838928, 2024). "The results demonstrated that DU145 cells overexpressing PTHLH exhibited enhanced proliferation, while the PTHLH inhibition group showed a marked decrease in cell proliferation, indicating that PTHLH promotes the proliferation of prostate cancer cells." (PMID 37838928, 2024). "However, it has been show in prostate cancer cells that while HIF1α and HIF2α are both able to bind to the PTHLH promoter, only HIF2α induces transcription." (PMID 33828987, 2021). "In addition, PTHLH induces MCP-1 in prostate cancer which can lead to increased proliferation." (PMID 19925653, 2009). "In the process of bone metastasis in lung, breast, and prostate cancer, tumor-driven osteoclastogenic factors, such as TGFβ1, PTHLH (parathyroid hormone-like hormone), and MMP-2 (Matrix metalloproteinase-2), facilitate osteolysis and homing of cancer cells to bone." (PMID 33917757, 2021).
osteoporosis (56 papers, 2004 to 2025). A condition of reduced bone mass, with decreased cortical thickness and a decrease in the number and size of the trabeculae of cancellous bone (but normal chemical composition), resulting in increased fracture incidence. "PTHLH gene encodes parathyroid hormone related protein (PTHrP) which has multiple functions including its anabolic activity on bone cells, and is used for osteoporosis treatment." (PMID 31249374, 2019). "To date, several genome-wide association studies (GWASs) have found hundreds of candidate genes associated with osteoporosis, including RANKL, SOST, ESR1, PTHLH, and DKK1." (PMID 37683138, 2023). "Contrarily, PTHLH was upregulated in non-osteoporosis patients." (PMID 40496565, 2025). "In part, this may contribute to the clinical success of a synthetic PTHLH-derived peptide drug, abaloparatide, in the treatment of osteoporosis in postmenopausal women." (PMID 34299213, 2021).